EGF (epidermal growth factor)
Diseases named in the same sentence as EGF in open-access papers (continued):
Sharing a sentence is not in itself a finding about the gene and the disease.
endothelial dysfunction (8 papers, 2017 to 2025). In vascular diseases, endothelial dysfunction is a systemic pathological state of the endothelium (the inner lining of blood vessels) and can be broadly defined as an imbalance between vasodilating and vasoconstricting substances produced by (or acting on) the endothelium. "IL-7R was expressed in vascular endothelial, and both recombinant IL-7 and EGF has shown therapeutic effect on endothelial dysfunction." (PMID 33119592, 2020). "Others are associated with anti-inflammation (IL-10 and TRAIL) or endothelial dysfunction (CD40 ligand, EGF)." (PMID 33138839, 2020). "Moreover, ticagrelor treatment decreased the circulating levels of epidermal growth factor (EGF), a marker of endothelial dysfunction." (PMID 33917744, 2021). "Levels of EGF, LRG1, and Angpt-2, evaluated as endothelial dysfunction biomarkers, are increased in DNE children and adolescents." (PMID 39311327, 2024). "In patients treated with ticagrelor or clopidogrel, we observed a negative correlation among changes in both SIRT1 and HES1 mRNA and serum levels of Epidermal Growth Factor (EGF), a marker of endothelial dysfunction found to be reduced by ticagrelor treatment in our previous study." (PMID 32106619, 2020).
keloid (8 papers, 2016 to 2025). An irregularly shaped, elevated mark on the skin caused by deposits of excessive amounts of collagen during wound healing. "TFM analyses demonstrated that normal dermal fibroblasts showed an EGF-mediated increase in traction stress, whereas both hypertrophy and keloid dermal fibroblasts exhibited EGF-mediated decreases." (PMID 33672186, 2021). "In this study, to elucidate the underlying mechanisms, we investigated the pivotal roles of epidermal growth factor (EGF) in modulating fibrotic phenotypes of keloid and hypertrophic dermal fibroblasts." (PMID 33672186, 2021). "In line with the tumor theory, several studies report overexpression and secretome emission of growth factors such as TGF-β, IGF-I, PDGF, and EGF in keloid tissue, with keloid cells demonstrating heightened sensitivity to these factors compared to normal cells." (PMID 41347148, 2025). "Fibroblasts isolated from keloids have been shown to produce 2 to 3 times the amount of collagen as fibroblasts from normal skin, so EGF could be one of the potential treatment options for keloids." (PMID 38046417, 2023). "Interestingly, our results indicated that exogenous EGF alleviated the fibrotic phenotype only in keloid dermal fibroblasts, evident by a significantly decreased gene expression of FSP-1, α-SMA and vimentin, as well as decreased vimentin protein expression." (PMID 33672186, 2021). "However, treatment of keloid dermal fibroblasts with EGF decreased their cell–matrix traction stress." (PMID 33672186, 2021). "Additionally, culture of keloid dermal fibroblasts with EGF resulted in decreased expression of FSP-1, α-SMA, and vimentin." (PMID 33672186, 2021). "These lncRNAs were associated with the related genes of keloid (ADAM12, COL6A3, and EGF)." (PMID 28101509, 2016). "Therefore, in this study, we investigated whether exogenous EGF could ameliorate the fibrotic phenotypes of keloid and hypertrophic scar-derived dermal fibroblasts through modulation of ECM remodeling." (PMID 33672186, 2021). "Abnormal growth of fibroblasts or hypertrophic scar tissue (keloids), or inflammatory factors over-expression, such as bFGF, TGF-β, PDGF, EGF, and CTGF in Dupuytren’s disease, can be found at the basis of the onset of these disorders." (PMID 36294816, 2022). "We observed that the specific and significant outgoing signal patterns of SC in the earlobe keloid were PTN, SEMA3, PDGF, and EGF." (PMID 36388926, 2022). "EGF-induced fibroblasts in keloid tissues show lower mobility than those of fibroblasts in normal tissues and undergo reduced mitosis." (PMID 39157347, 2024). "As previously reported, EGF treatment of all dermal fibroblasts significantly induced an increase in MMP-1 expression, and both normal and keloid dermal fibroblasts showed increased MMP-9 expression, whereas hypertrophic dermal fibroblasts showed a significant decrease in MMP-9 expression." (PMID 33672186, 2021).
lupus nephritis (8 papers, 2019 to 2026). Glomerulonephritis in the context of systemic lupus erythematosus. "Urinary epidermal growth factor (EGF) was identified by Liquid Chromatography with tandem mass spectrometry (LC-MS/MS) to be associated with renal interstitial fibrosis and long-term adverse kidney outcomes in lupus nephritis." (PMID 36941570, 2023). "EGF is a chemoattractant for monocytes, implicated with the recruitment of monocytes at the sites of inflammation, whereas urine epidermal growth factor (EGF) levels might serve as a potential biomarker of response to treatment in patients with Lupus Nephritis (LN)." (PMID 37072752, 2023). "EGF or EGF/MCP1 ratio have been shown to correlate with prognosis in primary glomerulonephritis, but there is limited information in lupus nephritis (LN)." (PMID 35271583, 2022).
malaria (8 papers, 2008 to 2022). Malaria is a serious and sometimes fatal disease caused by a parasite that commonly infects a certain type of mosquito which feeds on humans. "As an example, outside of malaria research, an epidermal growth factor null mutation on a CF-1 background results in early embryonic death, whereas homozygous mutants on a 129/Sv background die at mid gestation." (PMID 22096530, 2011). "Pfs28 contains epidermal growth factor (EGF)-like domains and is part of a family of sexual stage malaria proteins that includes the related vaccine antigen Pfs25." (PMID 36379968, 2022). "The first and most advanced transmission-blocking malaria vaccine candidate is Pfs25, a 24 kDa post-fertilization macrogamete/zygote surface antigen featuring four epidermal growth factor (EGF)-like domains." (PMID 26625934, 2015). "This fragment has been the focus of malaria vaccine development and consists of two epidermal growth factors (EGF)-like domains, each containing six cysteine residues, which are thought to have an important function in erythrocyte invasion." (PMID 20846388, 2010). "The MSP-1 19kDa contains two cysteine-rich epidermal growth factor (EGF)-like motifs that play an important role in erythrocyte invasion, making it an ideal target of inhibitory antibodies for blocking parasite invasion of erythrocytes and therefore an ideal candidate for a malaria vaccine." (PMID 23978002, 2013).
malignant glioma (8 papers, 2004 to 2022). A grade III or grade IV glioma arising from the central nervous system. "The recombinant anti-tumor, which is composed of epidermal growth factor (EGF) and the catalytic domain of the diphtheria toxin, was found to induce autophagy in malignant glioma cells to generate anti-tumor effects." (PMID 28753959, 2017). "In a previous study, a polymorphism in the 5′-untranslated region of the epidermal growth factor (EGF) gene, a natural ligand of the EGFR, was identified to play an important role in the pathogenesis of malignant gliomas." (PMID 22662167, 2012). "Epidermal growth factor receptor and its main ligands EGF and transforming growth factor alpha (TGFα) are commonly overexpressed in malignant glioma." (PMID 15305185, 2004). "In particular, it has been shown that TRPC1 is essential for chemotactic migration in human malignant gliomas in response to chemoattractant growth factors like epidermal growth factor (EGF) and platelet-derived growth factor (PDGF) which affect TRPC1 activity through different signaling pathways." (PMID 33928077, 2021). "The rationale to target the VEGF and EGF axis therefore seems obvious in malignant glioma." (PMID 15305185, 2004).
myopia (8 papers, 2021 to 2025). "EGF and its family members may thus belong to the list of molecules which were associated with the development of experimental myopia in previous investigations." (PMID 35477375, 2022). "EFEMP1 is typically characterized by a structural domain rich in epidermal growth factor (EGF), while EGF has been proven to be highly associated with myopia." (PMID 36891459, 2023). "Accordingly, clinical studies have shown an increased intraocular concentration of various growth factors, including EGF, in eyes with exudative/neovascular AMD and in eyes with pathologic myopia and macular neovascularization." (PMID 40852622, 2025). "This analysis indicated that INFG, TNF, IL1B, EGF, HGF and OSM would be predicted to stimulate recovery from induced myopia (activators)." (PMID 38390290, 2023). "In our results the most common significant pathways/processes that could be related to myopia were axon guidance, transcription, TGF-β signaling pathway, insulin signaling, focal adhesion, MAPK signaling pathway, and EGF-EGFR signaling pathway." (PMID 36685896, 2022). "To further elucidate the potential association of EGF and its family members with the process of myopic axial elongation in humans, we undertook this study to examine the intraocular concentration of EGF in the aqueous humor of non-highly patients and patients with high myopia." (PMID 34050811, 2021).
pheochromocytoma (8 papers, 2006 to 2025). "To integrate the inside-out and outside-in approaches, we used a microfluidic system to deliver periodic pseudo-sinusoidal pulses of EGF or NGF to pheochromocytoma cells and measured cell differentiation as a function of input frequency (outside-in approach)." (PMID 40508091, 2025). "The cell differentiation response of pheochromocytoma cells to different frequencies of pseudo-sinusoidal modulated EGF or NGF concentrations was examined for the first time in this paper." (PMID 40508091, 2025). "As noted in the introduction, we reported that pheochromocytoma cells underwent EGF-frequency-dependent cell population growth rates with negative, zero and positive rates being documented." (PMID 40508091, 2025). "Mutant huntingtin inhibits the activation of Akt induced by epidermal growth factor stimulation in rat pheochromocytoma cells." (PMID 23300147, 2013). "VGSCs have been found to be regulated by growth factors, such as fibroblast growth factor (FGF), nerve growth factor (NGF), epidermal growth factor (EGF), in various human and rat cell lines, such as pheochromocytoma PC12 cells and rat PCa Mat-LyLu cells." (PMID 18036246, 2007). "Rat pheochromocytoma cell line, PC-12, is well-studied that sustained activity of ERK by neuronal growth factor (NGF) stimulation leads cells to be differentiated, while transient activation kinetics from epidermal growth factor (EGF) induces proliferation." (PMID 30042437, 2018). "Similarly, nerve growth factor (NGF) stimulation of PC-12 pheochromocytoma cells as opposed to epidermal growth factor (EGF) stimulation leads to sustained high-level ERK1/2 activation and not a proliferative, but a differentiation response." (PMID 22784513, 2012).
small cell lung carcinoma (8 papers, 1995 to 2021). Small cell lung cancer (SCLC) is a highly aggressive malignant neoplasm, accounting for 10-15% of lung cancer cases, characterized byrapid growth, and early metastasis. "We here report that (−)-epigallocatechin gallate (EGCG) inhibited programmed cell death ligand 1 (PD-L1) expression in non–small-cell lung cancer cells, induced by both interferon (IFN)-γ and epidermal growth factor (EGF)." (PMID 30126206, 2018).
brain injury (7 papers, 2014 to 2019). Acute and chronic (see also brain INJURIES, CHRONIC) injuries to the brain, including the cerebral hemispheres, CEREBELLUM, and brain STEM. "In another study, induction of striatal neurogenesis by the intraventricular administration of brain-derived neurotrophic factor (BDNF) and EGF promoted functional recovery in a mouse model of neonatal hypoxic-ischemic brain injury." (PMID 28173860, 2017). "In this study, we assessed the importance of insulin-like growth factor (IGF) and epidermal growth factor (EGF) receptor co-signaling for rat neural precursor (NP) cell proliferation and self-renewal in the context of a developmental brain injury that is associated with cerebral palsy." (PMID 24904523, 2014). "Enhanced expression of BDNF, EGF, EPO, and bNGF after cerebral ischemia or traumatic brain injuries may contribute to the activation of neurogenesis in the SVZ." (PMID 27832087, 2016).
cholestasis (7 papers, 2014 to 2024). Impairment of the bile flow caused by obstruction within the liver, or outside the liver in the bile duct system. "Early cholestasis or an increase of epidermal growth factor could be one explanation for the observed increase in GGT with increasing fibrosis severity." (PMID 38926648, 2024). "In pathological conditions like cholestasis and fibrosis, EGF may impact the balance between cholangiocytes and hepatocytes by modulating β-catenin activity." (PMID 39040044, 2024). "Stimulations such as O.viverrini infection or PSC cause cholestasis and chronic inflammation of the bile duct, which can induce a variety of cytokines including IL-6, platelet-derived growth factor (PDGF), and epidermal growth factor (EGF)." (PMID 29029413, 2017).
colorectal tumor (7 papers, 2013 to 2023). "Clearly, the LIM1899 cell line is dependent on the EGFR signalling pathway for proliferation in vitro; this result is rather unexpected given that these cells harbour a KRAS mutation, which, in the majority of colorectal tumours, circumvents the EGF signalling pathway inhibition in the clinic." (PMID 35301819, 2022). "In the present study, we used EGF as a cell cycle inducer to get more cell-dividing colorectal tumor cells, which were more sensitive to commonly used chemotherapy agent 5-FU in vivo and in vitro." (PMID 29108242, 2017). "In this study, we present the applicability of imaging epidermal growth factor (EGF) receptor levels in preclinical models of COLO205 carcinoma cells in vitro, mice with orthotopic tumors and ex vivo colorectal tumor biopsies, using EGF-labeled with IRDye800CW (EGF-NIR)." (PMID 23857061, 2013). "In another study, this research group targeted EGFR-overexpression of colorectal tumor cells by functionalizing PLGA nanocarriers with epidermal growth factor (EGF), followed by co-loading of 5-FU and perfluorocarbon (EGF-PLGA-5-FU-PFC)." (PMID 34066710, 2021).
glomerulonephritis (7 papers, 2013 to 2026). A renal disorder characterized by damage in the glomeruli. "A rat model of nephrotoxic nephritis was used to investigate the therapeutic effects of an anti-lectin-epidermal growth factor (EGF) antibody on glomerulonephritis." (PMID 23627732, 2013). "To prove our hypothesis that glucocorticoids suppress crescent formation and glomerulonephritis through blocking EGF signaling in podocytes, we generated a rat model of accelerated anti-GBM nephritis." (PMID 35223886, 2022). "Tubular proteins, such as EGF may be better predictive markers than proteinuria or albuminuria for the prognosis of not only glomerulonephritis but also renal transplantation in patients." (PMID 31906817, 2020). "Urinary levels of EGF and EGF/MCP-1 ratios are inversely correlated with the extent of tubulointerstitial damage and determined renal prognosis in glomerulonephritis." (PMID 29577044, 2018).
IgA nephropathy (7 papers, 2019 to 2024). "This study investigated the association between urinary epidermal growth factor (EGF) and complete remission (CR) of proteinuria in children with IgA nephropathy (IgAN)." (PMID 36864281, 2023). "Earlier, prediction of outcome in IgA nephropathy and obstructive uropathy was found to be better with EGF/MCP-1 ratio than either cytokine on its own." (PMID 35271583, 2022). "In patients with IgA nephropathy, both renal EGF expression and urine EGF excretion are reduced at baseline and negatively correlated with disease progression." (PMID 35059432, 2021). "EGF/MCP-1 ratio may be superior to EGF or MCP-1 alone in predicting outcome in IgA nephropathy." (PMID 35271583, 2022). "The predictive power of urinary EGF was improved by combining it with MCP-1 into a uEGF/uMCP-1 ratio, which had priorly been shown to have predictive values in IgA nephropathy and for kidney fibrosis in primary glomerulonephritis." (PMID 37298105, 2023).
metastatic tumors (7 papers, 2010 to 2022). "The vascular endothelial growth factor (VEGF) and its receptors as well as the epidermal growth factor (EGF) and its corresponding receptors have been intensively screened as potential therapeutic targets for the treatment of metastatic tumor growth." (PMID 36264073, 2022). "In addition, we found that EGF is the major tumor‐derived factor in the lymph from metastatic tumor‐bearing animals compared to nonmetastatic tumor‐bearing animals and that the receptor for EGF is expressed in LCTCs but not BCTCs." (PMID 31026363, 2019).
multiple sclerosis (7 papers, 2011 to 2025). A progressive autoimmune disorder affecting the central nervous system resulting in demyelination. "Reduced levels of EGF have been linked to demyelination, which could cause multiple sclerosis (MS)." (PMID 40508163, 2025). "Collecting the literature used in this review began at the time of our studies of EGF as a physiological mediator of cobalamin (Cbl) myelinotrophism in human and rat CNS, and continued during our studies of CNS EGF levels in multiple sclerosis (MS)." (PMID 33151415, 2022). "EGF levels are significantly lower in the cerebrospinal fluid and spinal cord of patients with multiple sclerosis (MS), which probably explains remyelination failure, also because of the EGF marginal role in immunology." (PMID 33151415, 2022). "GS would particularly like to thank the anonymous Members of the Scientific Committee of the UK Multiple Sclerosis Tissue Bank at Imperial College, London, for approving his study of EGF in MS as this prompted the considerations made in this article." (PMID 34899572, 2021). "Moreover, an EGF antibody has been used to neutralize EGF in the animal model of multiple sclerosis and exhibits therapeutic effects by promoting oligodendrogenesis and ameliorating pathologic status." (PMID 34725188, 2021). "Interestingly, EGF is decreased in liquor from multiple sclerosis patients, while increased in the synovial fluid of RA patients, where it may regulate the inflammatory process." (PMID 21533026, 2011). "In contrast, the levels of EGF (nominal P = 0.005), CCL17 (nominal P = 0.03) and CD40.L (nominal P = 0.03) did change in relapsing–remitting multiple sclerosis as well, implying that these proteins are not suitable as markers for conversion." (PMID 38978729, 2024).
pneumonia (7 papers, 2016 to 2023). An acute, acute and chronic, or chronic inflammation focally or diffusely affecting the lung parenchyma, caused by an infection in one or both of the lungs (by bacteria, viruses, fungi, or mycoplasma.). "Pneumonia lung injury, characterized by computer tomography, positively correlated with levels of EGF, IP-10, MCP-3 levels and negatively with IL-12 p40." (PMID 36012146, 2022). "For example, systemic EGF decreases 7-day mortality in murine models of pneumonia and general peritonitis." (PMID 33004693, 2020). "PICFLU - The adjusted BS4 module containing EGF, Eotaxin, FGF-2, Fractalkine (FKN), GRO, IFN-α2, IL-12-P70, IL-7, MDC, and sCD40-L was negatively associated with shock, pneumonia-ARDS and ECMO or death (odds ratio 0.463, 0.598, 0.494, FWER-p = 0.0002, 0.0155, 0.0283, respectively)." (PMID 31275311, 2019). "It is interesting to note that the level of EGF was significantly higher in the recovered patients compared to fatal cases, whereas the level of TGF-α was generally higher in the patients that suffered from severe pneumonia compared to mild cases." (PMID 27146253, 2016). "Interestingly, in the pneumonia model, EGF does not improve lung pathology, but instead prevents pneumonia-induced GI mucosal injury." (PMID 33004693, 2020).